ACTR3P3 (ACTR3 pseudogene 3)
Gene: Processed pseudogene on chromosome 3 (101,163,094 to 101,163,986, forward strand). Ensembl gene ENSG00000242573.
Diseases named in the same sentence as ACTR3P3 in open-access papers:
ACTR3P3 is named in the same sentence as 1 disease in open-access papers, as found by Europe PMC text mining. Sharing a sentence is not in itself a finding about the gene and the disease.
ACTR3P3 shares sentences with these, for which no sentence is quoted: COVID-19 (1 paper).